LDHA (lactate dehydrogenase A)
Diseases named in the same sentence as LDHA in open-access papers (continued):
Sharing a sentence is not in itself a finding about the gene and the disease.
tumor (continued). "In the present study, we identified five genes (LDHA, PPAT, BFSP1, NR0B1, and PFKFB4) associated with the tumour immune microenvironment in HCC patient cohorts that may be applied as potential biomarkers of HCC immunotherapy outcome." (PMID 33407546, 2021). "This study elucidates a new epigenetic regulation mechanism in which KDM6B regulates tumor metastasis by directly mediating H3K27me3 demethylation of the glycolysis-related gene LDHA, thereby leading to increased LDHA expression and facilitated tumor metastasis in OS." (PMID 33664867, 2021). "Via the inducing L‐lactate production of LDHA overexpressed cells, extracellular acidification may play crucial roles in tumor proliferation, angiogenesis, the epithelial‐to‐mesenchymal transition, local invasion, and the formation of distant metastases." (PMID 34185423, 2021). "Moreover, serum LDHA levels are related to burthen of tumor and poor clinical outcomes to immune checkpoint (such as PD1 and CTLA4) blockade therapy." (PMID 34852326, 2021). "Tumor cells absorb a large amount of glucose, convert pyruvate to lactic acid through lactate dehydrogenase A (LDH-A), a key enzyme in glycolysis; and oxidize nicotinamide adenine dinucleotide hydride (NADH) to nicotinamide adenine dinucleotide (NAD+) at the same time." (PMID 33859941, 2021). "Although previous studies have shown that targeting LDHA attenuates tumor progression and metastasis, the molecular mechanism is still largely unknown." (PMID 33795650, 2021). "Lactate dehydrogenase-A (LDH-A) has been shown to act as the key enzyme in the glycolytic pathway by catalyzing the interconversion of pyruvate and lactate and plays a critical role in tumor maintenance." (PMID 34919531, 2021). "Moreover, among the different isoenzymes of LDH, two of them—LDHB and LDHA—were reported as deregulated proteins in cancer cells and are involved in the regulation of tumor–stroma nutrient exchange." (PMID 33802597, 2021). "LDHA generally promotes tumor progression by strengthening aerobic glycolysis." (PMID 34307169, 2021). "To investigate whether lactic acid is responsible for tumor invasion in PAs, we measured the levels of LDHA and LAMP2 expression in noninvasive human PAs (n = 32) by qRT-PCR and compared them with those in invasive PA samples (n = 32)." (PMID 33664865, 2021). "Therefore, targeting the glutamine metabolism, as well as silencing the activity of LDHA, provide promising strategies to reduce tumor progression, as demonstrated in preclinical tumor models." (PMID 34359663, 2021). "LDHA, β-catenin, and PCNA increased in the tumour tissues induced by injection of APC-mutated CRC cells expressing control shRNA and were significantly reduced in those generated by injection of the identical cells expressing PKM2 shRNA, as shown by IHC and western blot analyses." (PMID 33071283, 2021). "The role of LDHA/LDH5 and lactate transporters (eg, the MCT family) and the pathway associated with glucose metabolism, energy homeostasis, hypoxia, and tumor microenvironment requires further investigations until the development of specific inhibitors for clinical use." (PMID 34185423, 2021). "Some lncRNAs have been reported to be involved in tumor glycolysis by regulating LDHA." (PMID 34404767, 2021). "By employing isoenzyme electrophoresis, we identified that serum LDHA‐transcribed isoenzymes‐5 (LDH‐5) level is negatively associated with patients’ overall survival, prognosis, tumor aggressiveness, and maybe a novel serum biomarker." (PMID 34185423, 2021). "In contrast, tumor growth was inhibited when LDHA was knocked down." (PMID 34404767, 2021). "Previous studies showed that LDHA could promote tumor cells proliferation, invasion, migration, tumor progression, and metastasis, and might be a potential therapeutic target." (PMID 33287749, 2020).
tumor (continued). "In addition, we previously reported that a selenobenzene compound harboring trifluoromethyl group, 1-(phenylseleno)-4-(trifluoromethyl) benzene, showed an anti-tumor effect thorough suppressing LDHA activity." (PMID 33199724, 2020). "Our results support this view, where high LDHA protein expression is a metabolic prerequisite for highly-active, highly-anabolic, rapidly-proliferating, and migrating cells, such as those found at the invasive front of the tumor." (PMID 33353120, 2020). "Thus GDC-0032 inhibition of LDHA expression in drug-sensitive tumor cells can be detected in vivo through decreased 13C label exchange between hyperpolarized [1-13C]pyruvate and the endogenous lactate pool." (PMID 32976773, 2020). "Correspondingly, we found a significant increase in LDHA in tumor tissues at the protein level." (PMID 32859246, 2020). "Therefore, it is likely that a decrease of the PA molecular species containing PUFA, arachidonic acid or DHA, cannot attenuate the activity of LDHA in tumor cells." (PMID 32947951, 2020). "Similarly, the blockage of LDHA in tumor cells improves the efficacy of anti-programmed cell death-1 (PD1) therapy." (PMID 33153193, 2020). "Interestingly, elevated expression of genes indicative of glycolysis (including GLUT1 and LDHA) in human RCC tumor tissues correlate with low CD8 tumor-infiltrating lymphocyte (TIL) abundance." (PMID 33036247, 2020). "Previous studies have shown that lactate dehydrogenase A (LDHA) is a key player of the Warburg effect in tumour cell metabolism, which catalyses the inter-conversion of pyruvate and L-lactate as well as NADH and NAD+ conversion, which are essential for the early steps of glycolysis." (PMID 32878019, 2020). "Thus, LDHA ensures the maintenance of a “fuel” supply in cancer cells in addition to supporting tumor growth and invasion even under hypoxic conditions." (PMID 33153193, 2020). "Therefore, the LDHA content can be used as a marker of anoxia, neovascularization, and poor tumor prognosis." (PMID 32076440, 2020). "LDHA is another gene with a differentially APA-modified pattern in candidate tumor types." (PMID 32626751, 2020). "LDHA expression was elevated in normal brain tissues as well as in tumour samples." (PMID 31187466, 2020). "Besides, HIF-1α is not only a transcriptional regulator of LDHA, but also coordinates components of cancer development and progression and anti-tumor immunity." (PMID 32034005, 2020). "Likewise, LDHA inhibition of ex vivo‐cultured lung tumor cells reduced the suppressive effects of tumor‐conditioned media on IFN‐α production by Flt3L‐differentiated BMDC." (PMID 32508018, 2020). "On the long list of factors that regulate tumor cell death, LDHA and LDHB are mentioned." (PMID 31035592, 2019). "Targeting of LDHA with siRNA or small molecule inhibitors has been reported to increase oxygen consumption and reactive oxygen species production, reduce glucose uptake and lactate production, and decrease tumor cell growth." (PMID 31527446, 2019). "The inhibition of LDHA was reported to induce oxidative stress and suppress tumor progression." (PMID 30926903, 2019). "This suggests that silencing LDHA can effectively inhibit OSCC tumor growth in mice." (PMID 31921691, 2019). "Interestingly, knockdown of LDHA had an effect similar to that of vitamin C treatment, in which the stressed mice displayed an obvious reduction in tumor volume compared with untreated controls." (PMID 30688660, 2019). "Moreover, LDHA inhibition decreased tumor growth in a mouse xenograft model transplanted with Cα OE cells." (PMID 30926903, 2019). "In this context, we examined whether targeting PKM2 and LDHA can alter tumor cell metabolism and inhibit tumor cell proliferation." (PMID 31527446, 2019). "Similarly, glucose uptake is also reduced by BBR, via inhibition glucose transporter 1 (GluT1), lactate dehydrogenase-A (LDH-A), and hexokinase-2 (HK-2) expression, which induces apoptosis and thus inhibits tumor growth and invasiveness." (PMID 31841506, 2019).
tumor (continued). "Finally, we concluded that LDHA is an excellent metabolic target for tumor therapy, based on CK2α derived aerobic glycolysis." (PMID 30926903, 2019). "LDHA phosphorylation also contributes to tumor metastasis via altering cell metabolism." (PMID 31146503, 2019). "This promiscuous enzymatic activity of LDHA might represent a metabolic response to multiple environmental stimuli including hypoxia and acidosis, conditions frequently found in tumor microenvironment of aggressive tumors." (PMID 31737570, 2019). "Additionally, Western blot analysis indicated that the protein level of LDHA was up-regulated in OSCC tumor tissues." (PMID 31921691, 2019). "Therefore, in recent years, it has been known that a targeted therapy in cancer has been proposed to inhibit the activity of LDHA via either natural or synthetic compounds to attenuate the tumor progression and invasiveness." (PMID 30886157, 2019). "Attenuation or disruption of LDHA resulted in reduced tumor growth, and the authors attributed the diminished tumorigenicity to the compromised ability of tumor cells to grow under hypoxia or the importance of LDHA for tumor-initiating cells, respectively." (PMID 31835667, 2019). "Thus, in this type of tumor cells, a different response to the LDHA inhibition is observed, which provides a novel insight into the signaling pathway, shifting cancer cells towards either apoptosis or autophagy." (PMID 31035592, 2019). "LDHA is not only involved in normal cells metabolism, but closely related to tumor malignancy." (PMID 31637133, 2019). "Other studies have demonstrated that RCC LDHA mRNA and protein expression are positively correlated with histological grade and clinical stage, and high LDHA expression is a strong independent predictor of tumor progression and poor survival." (PMID 30189677, 2018). "Additionally, LDHA indirectly promotes tumor survival by protecting the tumor from reactive oxygen species (ROS) damage." (PMID 30403008, 2018). "Moreover, although in our differential gene expression analyses LDHA mRNA expression was not sufficiently higher in HCC livers compared to healthy and surrounding non-tumor livers, it seems that LDHA expression has a prognostic value in HCC." (PMID 30430110, 2018). "Downregulation of LDHA in cancer cells by siRNA or shRNA stimulates mitochondrial respiration and reduces cellular proliferative and tumorigenic potential in cancer cells in vitro and in tumor xenografts." (PMID 29541451, 2018). "Additionally, Seth et al86 found in K‐Ras‐induced cancer mouse model that LDHA deletion diminished PD‐L1+ tumor cells but elevated CD3+ and CD8+ T cells, suggesting significant immune activation in these mice." (PMID 30403008, 2018). "Thus, the importance of LDHA expression in cancer has been demonstrated in numerous studies, where knockdown or inhibition of LDHA impedes tumor growth." (PMID 30087897, 2018). "Thus, the importance of LDHA and tyrosine phosphorylation of LDHA in promoting tumor growth appears to be dependent on the cellular context." (PMID 30087897, 2018). "In addition, we also determined that the expression of the enzymes GLUT1, HK2, PKM2, and LDHA decreased in tumor tissue sections from the xenografts formed by GPx1 silencing in SW1990 cells." (PMID 30538220, 2018). "The main mechanism of LDHA suppression of immunity is the increase in lactate output, which could impair function of tumor‐suppressive immune factors." (PMID 30403008, 2018). "Finally, overexpression of LDHA can also promote tumor growth by preventing necrosis in hypoxic environment." (PMID 30403008, 2018). "Additionally, elevated levels of LDHA are markers of many tumours, the majority of them are highly glycolytic, and high LDHA levels are related with poor prognosis, for instance in several human malignancies." (PMID 29199484, 2018).
tumor (continued). "At the same time, clinical trials have shown that cancer patients with enhanced LDHA expression could significantly benefit from anti‐angiogenic therapy, suggesting that LDHA may accelerate tumor progression by facilitating angiogenesis." (PMID 30403008, 2018). "The co-expression of NR_028500 and LDHA implies that NR_028500 may be involved in the anaerobic glycolysis of tumor cells." (PMID 28076325, 2017). "We investigated JMJD2A and LDHA expression in NPC tumor specimens using IHC." (PMID 28693517, 2017). "Furthermore, the statistical results showed that the expression level of LDHA was positively correlated with disease stage and size, and increased LDHA expression was also correlated with decreased tumor differentiation." (PMID 28193910, 2017). "LDHA, a pivotal metabolic enzyme in glycolysis and the Warburg effect, converts pyruvate into lactate for extracellular secretion, remodels the tumour microenvironment, and promotes tumour invasion and metastasis." (PMID 28516914, 2017). "Although the observation on the absence of anaerobic glycolysis-associated marker fits well with increased intracellular alkalinity at ‘very low’ pH, we wondered how tumor cells at pH 3.4 were able to generate high levels of ATP to sustain high levels of cAMP, if LDHA levels were low." (PMID 28299282, 2017). "In vivo, LDHA overexpression promoted tumor growth, and oxamate delayed tumor growth." (PMID 28680051, 2017). "Our data indicate miR-200c is a tumor suppressor that directly targets LDHA." (PMID 28978061, 2017). "It was found that LDHA was over-expressed and related to tumor stages." (PMID 28193910, 2017). "LDHA overexpression is required for c-Myc-mediated transformation and tumor growth." (PMID 26918353, 2016). "Together, these studies suggest that LDHA inhibition could be a well‐tolerated therapy that will impede tumor growth and metastasis." (PMID 26269128, 2016). "LDHA is a key enzyme in glycolysis that plays an oncogene role in the metabolism of tumor cells." (PMID 27458165, 2016). "The results showed that ectopic expression of LDHA in U251 cells led to a significant increase in tumor size and tumor weight and transfection of miR200b could abrogate this effect caused by LDHA." (PMID 27374173, 2016). "Removing FAO as a substrate for TCA, and therefore LDHA activity, could lower tumor extracellular pH." (PMID 26962408, 2016). "Moreover, we perform xenograft experiments to further investigate the biologic function of miR-200b and LDHA in tumor growth." (PMID 27374173, 2016). "Both PKM2 and LDHA were overexpressed in tumour cells compared with normal pancreatic tissue." (PMID 26989901, 2016). "Therefore, the importance of LDHA in cell growth and survival is likely to be dependent on tumor metabolic phenotype, reliance on LDHA and microenvironmental influences." (PMID 26269128, 2016). "We then explored whether the tumor suppressor function of miR-34b-3 and miR-449a depends on LDHA expression." (PMID 27458165, 2016). "Furthermore, LDHA overexpression rescued the miR-34b-3 and miR-449a induced tumor inhibition effect in CNE2 cells." (PMID 27458165, 2016). "In this study, we showed that the HIF-1α was downregulated by LDHA-siRNA combined with RT, suggesting hypoxia could be suppressed by reduced LDHA, thus leading to inhibition of tumor survival genes and promoting radiosensitization." (PMID 27708237, 2016). "The enzyme LDHA is a key metabolic enzyme in aerobic glycolysis and considered as a tumor promoter." (PMID 27158819, 2016). "Although MEK/ERK could potentially modulate multiple downstream targets, our data clearly demonstrated that inhibiting MEK/ERK leads to reduced LDHA and tumor inhibition." (PMID 27150057, 2016). "In the TMA cohort, the expression of PKM2 and LDHA correlated with tumour size." (PMID 26989901, 2016). "It is well known that in addition to the Warburg effect, expression of PKM2 and LDHA in tumour tissues may be regulated by Hypoxia inducible factor 1-alpha (HIF1a) and c-Myc." (PMID 25880801, 2015).
tumor (continued). "Furthermore, decreased levels of LDHA were related to inhibition of tumour xenograft maintenance and progression." (PMID 25880801, 2015). "LDHA plays a key role in tumor initiation, maintenance and progression." (PMID 26121691, 2015). "By using two PC cell lines, PC-3 and DU145, we asked whether the elevated LDHA was essential for tumor progression and whether LDHA altered tumor microenvironment that favors tumor growth or metastasis." (PMID 25983002, 2015). "Lactate dehydrogenase A (LDHA) is frequently overexpressed in tumor cells." (PMID 26062441, 2015). "Several mechanisms by which LDHA suppression induces inhibition of tumor progression are revealed." (PMID 25983002, 2015). "Collectively, these data above demonstrated that LDHA favors tumor growth and metastasis in PC." (PMID 25983002, 2015). "SUVmax correlated with tumor size; expression of GLUT1, HK1, and LDHA; and NIH risk group." (PMID 26509967, 2015). "Moreover, NADH-dependent LDHA regenerates NAD + and competes with the mitochondrial NADH/NAD + shuttle system, which is decisive for mitochondrial activity associated with tumor metabolism." (PMID 24884974, 2014). "Moreover, there was a statistically significant stepwise increase in LDHA-high expression and tumor stage." (PMID 24885701, 2014). "In particular, the tumor cells near the necrotic tissues markedly expressed LDHA." (PMID 23456655, 2013). "Our findings suggest that ERRα may influence tumor aggressiveness by metabolic modification and modulation of the LDHA/LDHB expression ratio." (PMID 23516535, 2013). "Increased LDHA levels seem to be mandatory in tumor initiation as well as maintenance." (PMID 22859959, 2012). "Thus, while both tumor types show an increased ratio of LDHA to B, SDHB-derived tumors show a significantly increased overall expression of LDH." (PMID 22859959, 2012). "Nevertheless, two key enzymes responsible for the maintenance of tumour glycolysis in aerobic conditions - lactate dehydrogenase A (LDHA) and pyruvate kinase type M2 (PKM2) - were among those identified in our analysis as up-regulated by STAT1 at both the gene and protein level." (PMID 19891767, 2009). "Thus, we hypothesize that the lactylation level of LDHA might influence tumor proliferation by modulating glycolysis." (PMID 41190808, 2026). "Moreover, the activation of key enzymes such as PKM and LDHA indicates that UBD may accelerate tumor cell energy metabolism by promoting lactate production in the downstream steps of glycolysis." (PMID 40692714, 2025). "Moreover, LDHA-mediated lactate production is a central driver of tumor proliferation." (PMID 41152975, 2025). "Notably, LDHA overexpression efficiency was limited, potentially due to high basal LDHA expression in tumor cell lines, which may explain the limited effect of circSMPD4 overexpression on LDHA levels." (PMID 40940312, 2025). "However, therapeutic success will require precision approaches that account for differences in metabolic programming among tumor cells and immune subsets, careful selection of molecular targets (e.g., LDHA, MCT1, GPR81), and strategies to minimize potential adverse effects on nonmalignant tissues." (PMID 40710349, 2025). "Additionally, metabolic reprogramming via LDHA is critical for NK cell-mediated tumor cytotoxicity." (PMID 40498022, 2025). "However, stiripentol treatment showed similar anti-tumor effects in both WT and LDHA-mKO mice." (PMID 38443336, 2024). "Notably, LDHA and its metabolic by‐product lactic acid are substantially up‐regulated in various rodent PH models, with reports indicating that LDHA up‐regulation can stimulate tumour progression." (PMID 39021353, 2024).